GFM1 (G elongation factor mitochondrial 1)
Description:
Mitochondrial GTPase that catalyzes the GTP-dependent ribosomal translocation step during translation elongation. During this step, the ribosome changes from the pre-translocational (PRE) to the post-translocational (POST) state as the newly formed A-site-bound peptidyl-tRNA and P-site-bound deacylated tRNA move to the P and E sites, respectively. Catalyzes the coordinated movement of the two tRNA molecules, the mRNA and conformational changes in the ribosome. Does not mediate the disassembly of ribosomes from messenger RNA at the termination of mitochondrial protein biosynthesis.
Synonyms: hEFG1; EFG; EFG1; GFM; EFGM; EGF1; mtEF-G1; COXPD1
Tractability: Small molecule: a structure with a bound ligand is known. PROTAC: ubiquitination databases record sites on it; its protein half-life has been measured.
Target class: Enzyme; Hydrolase
Gene: Protein-coding gene on chromosome 3 (158,644,516 to 158,695,836, forward strand). Ensembl gene ENSG00000168827.
Subcellular location: Mitochondrion
Subcellular location (Human Protein Atlas): Mitochondria; Nucleoplasm
Pathways (Reactome):
Metabolism of proteins: Mitochondrial translation elongation
Gene Ontology:
Molecular function: GTPase activity; protein binding; RNA binding; translation elongation factor activity; GTP binding
Biological process: mitochondrial translational elongation; translation; translational elongation
Cellular component: mitochondrion; mitochondrial matrix
Genetic constraint (gnomAD): Loss-of-function variants: 46 observed, 70.96 expected, observed/expected ratio (o/e) 0.65, 90% interval 0.51 to 0.83. The upper end of that interval is the gene's LOEUF score, 0.83, which puts it in group 3 of 6, group 1 being the genes least tolerant of losing a copy. Missense variants: 640 observed, 723.07 expected, observed/expected ratio (o/e) 0.89, 90% interval 0.83 to 0.94. Synonymous variants: 224 observed, 255 expected, observed/expected ratio (o/e) 0.88, 90% interval 0.79 to 0.98.
Gene-disease validity (ClinGen):
ClinGen rates the evidence that GFM1 causes each of these diseases.
Leigh syndrome (autosomal recessive): Moderate. A progressive neurological disease defined by specific neuropathological features associating brainstem and basal ganglia lesions.
Homologues: Orthologues: chimpanzee GFM1 (99% identical), macaque GFM1 (97% identical), rabbit GFM1 (93% identical), dog GFM1 (93% identical), pig GFM1 (92% identical), guinea pig GFM1 (92% identical), mouse Gfm1 (91% identical), rat Gfm1 (91% identical), tropical clawed frog gfm1 (82% identical), zebrafish gfm1 (78% identical), Drosophila melanogaster mEFG1 (64% identical), Caenorhabditis elegans gfm-1 (54% identical). Paralogues in human: GFM2 (34% identical), EEF2 (24% identical), EFL1 (23% identical), EFTUD2 (20% identical), GUF1 (16% identical), EEF1A1 (14% identical), EEF1A2 (14% identical), HBS1L (13% identical), TUFM (12% identical), MTIF2 (12% identical), EEFSEC (11% identical), GSPT1 (11% identical), and 6 more.
Diseases named in the same sentence as GFM1 in open-access papers:
GFM1 is named in the same sentence as 67 diseases in open-access papers, as found by Europe PMC text mining. Sharing a sentence is not in itself a finding about the gene and the disease. The quoted sentences say what the papers report.
liver failure (3 papers, 2015 to 2026). A liver disease characterized by the liver losing or has lost all of its function. "Liver dysfunction (including hepatomegaly, liver failure, hepatic cytolysis) had attracted much attention in GFM1‐related diseases." (PMID 32776492, 2020).
Dystonia (2 papers, 2020 to 2025). An abnormally increased muscular tone that causes fixed abnormal postures. "Disease caused by GFM1 mutations mainly affects the patient's neurologic central nervous system, presented as spasticity, dystonia, epilepsy, and so on." (PMID 32776492, 2020).
liver disease (2 papers, 2020 to 2024). "The majority of GFM1 SNPs were linked to myocardial infarction, cardiomyopathy, heart failure, Alzheimer’s disease/dementia, diabetes, kidney failure, liver disease, and death." (PMID 38293129, 2024). "We translated their relevance to humans using UK Biobank data and showed that variants in RICTOR and GFM1 are associated with an elevated risk of age-related heart disease, dementia, diabetes, kidney, and liver diseases." (PMID 38293129, 2024). "GFM1 variants were reported to be associated with neurological diseases and liver diseases in a few cases." (PMID 32776492, 2020).
OXPHOS disease (2 papers, 2016 to 2021). "A comprehensive genomic analysis revealed that GFM1 is one gene mutation known to cause OXPHOS disease in patients with childhood-onset mitochondrial respiratory chain complex deficiencies." (PMID 34277617, 2021). "In conclusion, GFM1 is one of the known gene mutations causing OXPHOS disease, and its mutations and abnormal expression are closely related to a series of mitochondrial diseases." (PMID 34277617, 2021).
aortic aneurysm (1 paper, 2024). A ruptured aneurysm located in the wall of the proximal portion of the descending aorta proceeding from the arch of the aorta. "Specifically, our results highlight distinct genomic regions implicated in the predisposition to cardiomyopathy and heart failure for GFM1, and heart failure and aortic aneurysm for RICTOR, diseases that negatively affect survival in humans." (PMID 38293129, 2024).
Blindness (1 paper, 2020). Blindness is the condition of lacking visual perception defined as a profound reduction in visual perception. "Interestingly, the case in our study showed symptoms of blindness and recurrent vomiting, suggesting that GFM1 mutations may also have an effect on the eyes and digestive system." (PMID 32776492, 2020).
delirium (1 paper, 2025). A disorder characterized by confusion; inattentiveness; disorientation; illusions; hallucinations; agitation; and in some instances autonomic nervous system overactivity. "There were eight protective genes (DHODH,DHRS7B,TOP1MT,CASP8,GFM1,CPT1B,TK2,GPD2), and four genes (SCP2,DMPK,GSTK1,SIRT3) that increased delirium risk, as shown inFigure 2, withp = 0.05 (dotted line); and false discovery rate (FDR) < 0.05 (red asterisks)." (PMID 41330563, 2025). "Our findings show that higher expression of 8 genes, includingDHODH,DHRS7B,TOP1MT,CASP8,GFM1,CPT1B,TK2, andGPD2, could decrease the risk of delirium." (PMID 41330563, 2025).
epilepsy (1 paper, 2020). A brain disorder characterized by episodes of abnormally increased neuronal discharge resulting in transient episodes of sensory or motor neurological dysfunction, or psychic dysfunction. "Here, we present a novel composition of two heterozygous mutations of GFM1 in a boy with epilepsy, mental retardation, and other unusual phenotypes." (PMID 32776492, 2020). "Epilepsy was also an important clinical manifestation of GFM1‐linked disease, about 41% of patients suffered from epilepsy." (PMID 32776492, 2020). "We present a novel compound heterozygous mutation of GFM1 with c.679G > A and c.1765‐2_1765‐1delAG deletion in a boy with epilepsy, mental retardation, and other symptoms." (PMID 32776492, 2020).
leprosy (1 paper, 2017). Leprosy is a chronic infectious disease affecting primarily the skin and peripheral nervous system. "Of note, among the GO term enrichments for upregulated genes after M. leprae antigen stimulation, we found the “release of cytochrome c from mitochondria” GO term (FDR of 3x10-3) However, the specific role of GFM1 in leprosy pathogenesis needs to be determined by functional studies." (PMID 28793313, 2017).
infection (25 papers, 2009 to 2025). The state of being infected such as from the introduction of a foreign agent such as serum, vaccine, antigenic substance or organism. "Interestingly, the integration of the functional genomics approach and GWAS data with the evolutionary genetics approach allowed us to identify reQTL for three genes, GFM1, CORO1C and CEP192, that likely have a major role against infection with M. leprae and/or T1R." (PMID 28793313, 2017).
tumor (14 papers, 2012 to 2025). "The expression of GFM1 was reported to be significantly elevated in LUSC tumor compared with normal tissues." (PMID 40568577, 2025). "Besides, we also validated the expression levels of LM.Sig using IHC staining, and the results indicated that the expression levels of CHEK2 and GFM1 were downregulated in normal lung tissues compared to tumor tissues." (PMID 40568577, 2025). "Four recurrent deleterious variants corresponding to the CHD1L (99.0%), GFM1 (91.7%), MEIS1 (90.6%) and NFX1 (93.8%) genes were found in the majority of the tumor samples in the study cohort, but in none of the normal controls." (PMID 30416686, 2018).
cancer (8 papers, 2017 to 2025). A tumor composed of atypical neoplastic, often pleomorphic cells that invade other tissues. "Machine learning models based on seven LM-related genes (CHEK2, LIPT1, TUFM, NDUFA10, AGK, PNPLA2, and GFM1) accurately predicted immunotherapy outcomes for multiple cancer types, including LUSC, and outperformed other currently known biomarkers." (PMID 40568577, 2025). "Several genetic variants had high mutation rates across the entire study group in comparison with normal ovarian controls, e.g. recurrent deleterious variants in the CHD1L, GFM1, MEIS1 and NFX1 genes, suggesting specificity to cancer." (PMID 30416686, 2018).
mitochondrial disease (7 papers, 2019 to 2026). "Our laboratory previously demonstrated that the combination of polydatin and nicotinamide holds promise as a therapeutic option for pathogenic GFM1 variant-related mitochondrial diseases by activating the mitochondrial unfolded protein response (mtUPR)." (PMID 40002401, 2025). "In this work, we have established a suitable cellular model for investigating mitochondrial diseases using fibroblasts derived from patients with mutations in the GFM1 gene." (PMID 38786005, 2024). "In this work, we explored new therapeutic options in mitochondrial diseases using fibroblasts and induced neurons derived from patients with mutations in the GFM1 gene." (PMID 38786005, 2024). "In this work, we establish that fibroblasts derived from patients with mutations in the GFM1 gene constitute a valuable experimental model for investigating mitochondrial diseases." (PMID 38786005, 2024). "Fibroblasts derived from a patient (GFM1) bearing two inherited, pathogenic heterozygous mutations on the G elongation factor mitochondrial 1 (GFM1) were used as a model of mitochondrial disease." (PMID 35581596, 2022). "Recently, a study reported a family that carries a novel GFM1 variant, which is associated with a rare fatal mitochondrial disease." (PMID 34277617, 2021).
GFM1 also shares sentences with these, for which no sentence is quoted: Encephalopathy (6 papers); breast carcinoma (2); candidiasis (2); co-infection (2); disseminated candidiasis (2); glioma (2); lymphoma (2); primary coenzyme Q10 deficiency (2); abscess (1); Alzheimer disease (1); Ataxia (1); atherosclerosis (1); bipolar disorder (1); Candidemia (1); cardiomyopathy (1); cerebral thrombosis (1); cholangiocarcinoma (1); CNS lymphomas (1); colon cancer (1); combined oxidative phosphorylation deficiency (1); congenital myopathies (1); dementia (1); denture stomatitis (1); diabetes (1); ear infection (1); fungal infection (1); gastric cancer (1); glycogen storage diseases (1); heart disease (1); heart failure (1).
A further 24 diseases each share a sentence with GFM1 in 1 paper.